ARRB1 (arrestin beta 1)
Diseases named in the same sentence as ARRB1 in open-access papers (continued):
Sharing a sentence is not in itself a finding about the gene and the disease.
tumor (continued). "Our findings highlight the importance of transcriptional co-regulatory mechanisms and ECM remodeling in tumor progression, as well as the potential predictive consequences of ARRB1, COL1A2, MED10, RSP3A and others." (PMID 40362431, 2025). "Specifically, low expression of ARRB1 promotes tumor growth enhancing the E2F1 survival function, while high expression of ARRB1 triggers E2F1 acetylation switching E2F1 function from pro-survival into pro-apoptotic." (PMID 36923256, 2023). "In this study, we undertook a comprehensive analysis of differential ARRB1 expression among 33 tumor types and normal tissues, and identified the clinical prognostic value and potential immunotherapeutic value of ARRB1 in a variety of tumors." (PMID 36213111, 2022). "Immunohistochemical staining results showed different expression levels of ARRB1 protein in 13 normal or tumor tissues." (PMID 36213111, 2022). "The results showed that ARRB1 expression was relatively high in low-grade KIRC and low-stage LUAD, further suggesting a potential relationship between ARRB1 and tumor prognosis and aggressiveness." (PMID 36213111, 2022). "Together, these results suggest that ARRB1 plays different roles in different tumors, even in different biological processes of the same tumor." (PMID 36213111, 2022). "Given that next-generation sequencing is widely used in tumor molecular typing to assist in diagnosis and treatment decision-making, clinical research on ARRB1 predicting the efficacy of immune checkpoint inhibitors deserves further exploration." (PMID 36213111, 2022). "At the same time, ARRB1 was closely correlated with the tumor immune microenvironment and indicators of immunotherapy efficacy, indicating its great potential as a reliable marker for predicting the efficacy of immunotherapy." (PMID 36213111, 2022). "Considering the significant connection identified between ARRB1 expression and tumor prognosis and immunity, GSEA was used to explore the potential biological implications and pathways associated with ARRB1 expression." (PMID 36213111, 2022). "In the present study, we explored the ARRB1 expression profile in 33 cancer types and investigated the potential impact of ARRB1 on prognosis for survival in cancer and the tumor immune microenvironment." (PMID 36213111, 2022). "Our findings suggested that ARRB1 generally correlated with many biological behaviors of cancer and plays different roles in different tumor types." (PMID 36213111, 2022). "For example, the tumor suppressive activity in T-ALL is at least partially attributable to ARRB1-mediated degradation of NOTCH1." (PMID 36452459, 2022). "Elucidating the mechanisms of ARRB1 regulation in the tumor immune microenvironment is a promising direction for the future." (PMID 36213111, 2022). "Clinical parameters such as patient survival, tumor stage, age, and gender were used to assess the prognostic value of ARRB1." (PMID 36213111, 2022). "The ARRB1 expression level in tumor tissues was significantly higher than that in CHOL control tissues." (PMID 36213111, 2022). "miR-223 targeted the 3 ’-UTR of ARRB1 to inhibit ARRB1 expression and effectively antagonized the tumor suppressive effect of ARRB1 in T-ALL." (PMID 36452459, 2022). "On the contrary, in the low-risk group, the expressions of IL3RA, CX3CR1, ARRB1, LIFR, and VIPR1 were higher than those in the high-risk group, which signified that they have a tumor suppressor effect." (PMID 35833114, 2022). "We further found that ARRB1 expression was significantly correlated with tumor stage in BRCA, ESCA, KIRC, TGCT, and THCA, while in some tumors, particularly KIRC and LUAD, ARRB1 expression was associated with better prognosis." (PMID 36213111, 2022). "ARRB1 was not only associated with a good prognosis in patients with KIRC and LUAD but was also lowly expressed in tumor tissue." (PMID 36213111, 2022).
tumor (continued). "Collectively, these results confirm that EZH2 is responsible for the impaired expression of miR‐326 and ARRB1 in MBs, which eliminates important checks of tumor growth." (PMID 32920979, 2021). "In accordance with this observation, ARRB1 KO clones exhibited significantly slower tumor growth in nude mice." (PMID 33920080, 2021). "As cell apoptosis and cell cycle arrest has been widely reported to affect the proliferation of tumor cells, we next detected the influences of ARRB1 on cell apoptosis and cell cycle distribution." (PMID 33753990, 2021). "High levels of ARRB1 expression were significantly correlated with tumor size (P= 0.015) and lymphatic metastasis (P= 0.009)." (PMID 33753990, 2021). "Here, we initially observed elevated levels of pro-inflammatory cytokines (most notably TNF), infiltration of inflammatory cells, and upregulation of four GPCR-associated genes (CCR10, P2RY8, ARRB1, and RGS10) in human HCC tumor and paracancerous specimens." (PMID 29445190, 2018). "By increasing glycolytic activity and decreasing mitochondrial function, an adaptive mechanism used by cancer cells to fuel their growth, ARRB1 would therefore act as a tumour promoter." (PMID 24837709, 2014). "In summary we present evidence that miR-525-3p is an important regulator of survival in normal and in tumor-derived cell lines, and that the direct targets ARRB1, HSPA9 and TXN1 each have a direct effect on survival after irradiation." (PMID 24147004, 2013). "In vivo studies corroborate the tumor-promoting effects of ARRB1-Δexon13." (PMID 40486495, 2025). "Third, given that ARRB1 deficiency simultaneously enhances T cell function and reduces MDSC populations, ARRB1 targeting could improve CAR-T cell therapy outcomes by creating a more favorable tumor microenvironment." (PMID 41373634, 2025). "Of note, in comparison to full-length ARRB1, an ARRB1 splicing variant (Arrb1 without exon 13) strongly promoted tumor growth, likely through regulating tumor glycolysis." (PMID 38299588, 2024). "Taken together, these data suggest that AEP-specific cleavage of DDX3X leads to nuclear translocation and that nuclear tDDX3X-C regulates oncogenic splicing in multiple kinds of malignant tumors, especially via PRDM2 and ARRB1, under tumor microenvironmental stimuli dependent on HIF1A." (PMID 37988165, 2023). "AEP/tDDX3x–induced PRDM2-Δexon 2 and ARRB1-Δexon 13 promote tumor malignancy." (PMID 37988165, 2023). "However, gain of the ARRB1-Δexon 13 isoform resulted in a stronger tumor-promoting capacity than that of the WT ARRB1." (PMID 37988165, 2023). "In addition, correlations between ARRB1 and predictors of immune checkpoint inhibitor (ICI) efficacy (tumor mutation burden [TMB], microsatellite instability [MSI], and Programmed cell death-ligand 1 [PD-L1])." (PMID 36213111, 2022). "Finally, we investigated the relationship between ARRB1 expression and immunotherapeutic responses in three independent tumor immunotherapy cohorts." (PMID 36213111, 2022). "Furthermore, high ARRB1 expression levels were significantly correlated with some tumor immune-related pathways." (PMID 36213111, 2022). "To further explore the potential role of ARRB1 in the tumor immune microenvironment, we first determined whether a correlation existed between ARRB1 and immune cell infiltration." (PMID 36213111, 2022). "By analyzing the potential relationship between ARRB1 expression and the prognosis of tumor patients in human pan-cancer, we first observed that in differentially expressed tumors, except for CHOL, ARRB1 expression was significantly higher in 17 normal tissues than in tumor tissues." (PMID 36213111, 2022). "Furthermore, considering that ARRB1 is not only associated with a good prognosis in KIRC and LUAD patients, but is also lowly expressed in both tumor tissues." (PMID 36213111, 2022). "Overall, ARRB1 has an important role in both the tumor and immune microenvironment." (PMID 36213111, 2022).
tumor (continued). "ARRB1 expression was significantly correlated with tumor stage in BRCA, ESCA, KIRC, TGCT, and THCA." (PMID 36213111, 2022). "In addition, correlation analysis of independent GEO cohorts also demonstrated relatively high expression of ARRB1 in low-stage LUAD and low-grade KIRC, which together suggested the possibility of ARRB1 as a tumor suppressor gene in KIRC and LUAD." (PMID 36213111, 2022). "Moreover, ARRB1 plays an important role in tumor cell epithelial-to-mesenchymal transition (EMT) and metabolic reprogramming, and also regulates important signaling pathways in tumors (Bagnato and Rosanò, 2019)." (PMID 36213111, 2022). "Although ARRB1 expression is low in most tumor tissues, several studies have suggested that ARRB1 may be a marker of poor prognosis in a small proportion of cancers." (PMID 36213111, 2022). "The results above suggested that ARRB1 plays important roles in GBC tumor progression in vitro." (PMID 33753990, 2021). "Consistently, TUNEL staining showed that suppressed ARRB1 could stimulated the apoptosis of tumor cells." (PMID 33753990, 2021). "After 28 days, we observed the tumor size distinctly diminished on account of ARRB1 downregulation." (PMID 33753990, 2021). "Although ARRB1 has recently been shown to also play an important role in tumor growth, metastasis, inflammation, and immunity, its relationship with distinct tumor types and the tumor immune microenvironment remains unclear." (PMID 36213111, 2022). "Thus, ARRB1-mediated regulation of GLUT1 highlights the role of ARRB1 as a tumor oncogene in BC." (PMID 33920080, 2021). "Moreover, the tumor-promoting effect of overexpression ARRB1 may be partially related the activations of TAK1/MAPK axis." (PMID 33753990, 2021). "Our results suggested that ARRB1 may be a putative tumor suppressor gene in LUAD." (PMID 34285141, 2021). "Most notably, after Vk*myc tumor implantation, we observed substantial increases in both CD4+ and CD8+ T cell populations in the spleens of ARRB1 knockout mice compared to wild-type littermate controls." (PMID 41373634, 2025). "Other studies have found higher expression of ARRB1 during HCC metastasis, and its upregulation correlates with tumor progression." (PMID 40275933, 2025). "The correlation of ARRB1 with stromal cells, immune cells, and immune modulators (immunosuppressants, immunostimulants, and MHC molecules) in the tumor immune microenvironment were all investigated." (PMID 36213111, 2022). "Through a series of in vitro and in vivo assays, we confirmed that inhibition of ARRB1 restrained the GBC cell proliferation, metastasis and tumor growth." (PMID 33753990, 2021). "In summary, our data show that ARRB1 is an important regulator of CSC characteristics and tumor cell growth in attachment independent conditions and in vivo." (PMID 33920080, 2021). "While ARRB1 functions as an oncogene and positively regulates expression of stem cell markers, ARRB2 functions as a tumor suppressor and negatively regulates stem cell properties." (PMID 33297302, 2020). "In the current study, the mean expression index of ARRB1 was found to be 1.4, 0.95, 0.83 and 0.4 for TANT (Tumor Adjacent Normal Tissue), stage 1, stage 2 and stage 3 respectively." (PMID 28559546, 2017). "The expression of ARRB1, FLNA, CALM3 and HTT was found to be localized predominantly in the cytoplasm of the tumor cells." (PMID 28559546, 2017). "The fact that initial tumor engraftment was similar between wild-type and knockout mice suggests that ARRB1 primarily affects the adaptive immune response rather than initial tumor seeding." (PMID 41373634, 2025). "An inverse expression of ARRB1 and ARRB2 both significantly correlated with tumor metastasis." (PMID 37196048, 2023). "For this reason, the fact that miR‐326 and ARRB1 appear to exert convergent tumor‐suppressive effects in human MBs is by no means incompatible with its demonstrated oncogenic effects in other cancer cells." (PMID 32920979, 2021).
tumor (continued). "We found that ARRB2, but not ARRB1, gene is significantly more expressed in ccRCC tumor compared to normal tissue." (PMID 29559707, 2018). "Whether in Oncomine or in UALCAN, ADRB2, ARRB1, BDNF, etc., had a lower expression in tumor group than normal tissues, whereas CBLC, GPI, and PAK1 had a higher expression in tumor group than normal tissues." (PMID 35833114, 2022).
cancer (30 papers, 2014 to 2025). A tumor composed of atypical neoplastic, often pleomorphic cells that invade other tissues. "More interestingly, ARRB1-Δexon 13–enhanced malignant growth of cancer cells is associated with glycolysis and the HIF-1 signaling pathway." (PMID 37988165, 2023). "Proliferation-related assays, including Cell Counting Kit-8 (CCK-8) and colony formation assays, were performed, and as expected, loss of PRDM2 or gain of the ARRB1-Δexon 13 isoform induced by AEP/tDDX3X-C promoted cancer cell proliferation." (PMID 37988165, 2023). "In this study, two biomarkers of immunotherapy (TMB and MSI) showed a significant association with ARRB1 expression in some cancers." (PMID 36213111, 2022). "The carcinogenic mechanism of inflammation linked to TGF-β or TNF-α and its regulation of ARRB1 in GBC or other cancers still needs to be fully elucidated." (PMID 33753990, 2021). "Notably, our prior research indicated that ARRB1 enhanced cancer cell growth through its association with glycolysis and the hypoxia-inducible factor 1 (HIF-1) signaling pathway." (PMID 40486495, 2025). "However, our data show that abrogation of ARRB1 in BC cells shifts the metabolic program towards mitochondrial oxidative phosphorylation, underlining the metabolic flexibility of cancer (stem cell-like) cells." (PMID 33920080, 2021). "Arrb1 encodes a multifunctional adaptor and scaffold protein regulating several signaling pathways critically involved in cell development in both physiological and pathological (i.e. cancer) contexts." (PMID 28716052, 2017). "Emerging evidence suggests that ARRB1 plays a critical role in regulating the self-renewal and growth of cancer cells." (PMID 40486495, 2025). "The expression level of ARRB1 in cancer stroma is significantly higher than in cancer epithelia, further validating its role in SOC stroma." (PMID 39985042, 2025). "To determine the effects of PRDM2-Δexon 2 and ARRB1-Δexon 13 isoforms on cancer cell function, we performed rescue experiments using the following groups of cancer cells: NC, AEP KD, AEP KD/tDDX3X-C res, AEP KD/PRDM2 KD, and AEP KD/ARRB1-Δexon 13 res cells." (PMID 37988165, 2023). "This is the first report to prospectively reveal the prognostic and therapeutic value of ARRB1 in 33 cancers." (PMID 36213111, 2022). "ARRB1 expression has some prognostic value in several cancers, among which KIRC and LUAD drew our attention." (PMID 36213111, 2022). "We further used HPA data to analyze the expression of ARRB1 protein in different cancer tissues and corresponding normal tissues." (PMID 36213111, 2022). "As a first step, we used a Cox proportional hazards regression model to analyze the association of ARRB1 expression with OS, PFS, DSS, and DFS in patients in pan-cancer." (PMID 36213111, 2022). "Other studies have shown that ARRB1 regulates several cancer-related cellular processes via diverse signal transduction pathways, including the Ras/Raf/MEK/ERK family, β-catenin/TCF4 signalling, Akt/GSK3β signalling, mTOR signalling and NF-κB signalling." (PMID 34380537, 2021). "According to the data, numerous genes (such as H2AFX, CDKN2A, TTF2, IKBKE, and UBE2I) were markedly upregulated in many cancer types, while some genes (such as ARRB1, LMO3, KHDRBS2, CIRBP, and RALYL) were remarkably downregulated in multiple cancer types." (PMID 35003212, 2021). "Many cancers are driven from CSCs and both ARRB1 and ARRB2 were shown to be crucial in regulating CSC self-renewal." (PMID 33297302, 2020). "Mechanistically, ARRB1-mediated epigenetic regulation of the tumor suppressor PTEN plays a key role in maintaining the self-renewal potential in the cancer stem cell-enriched CD34+CD38-CD19+ population of B-ALL." (PMID 33297302, 2020). "Depletion of ARRB2 (in contrast to ARRB1) abrogated self-renewal of bcCML cancer stem cells and promoted differentiation as shown in in serial transplantation assays in mice." (PMID 33297302, 2020).